TRPM8 (transient receptor potential cation channel subfamily M member 8)
Diseases named in the same sentence as TRPM8 in open-access papers (continued):
Sharing a sentence is not in itself a finding about the gene and the disease.
prostate carcinoma (continued). "Androgen receptor was also reported to modulate both expression and activity of the TRPM8 channel in a human prostate cancer cell line (PC3)." (PMID 33614639, 2021). "For example, an increase in the expression of the Ca2+ channels TRPV2 in prostate cancer, and TRPM8 in squamous cell carcinoma resulted in induction of MMP-2 and MMP-9, respectively." (PMID 33802790, 2021). "For example, TRPV1 is increased in prostate, colon and pancreas cancer cells, and TRPM8 has been found in breast, colon, lung and prostate cancer cells." (PMID 33614639, 2021). "Selected antagonists interfere in non-genomic androgen action and abolish the androgen-induced androgen receptor/TRPM8 complex assembly as well as the increase in intracellular calcium levels in prostate cancer cells." (PMID 34853378, 2021). "TRPM8 channel has been described as a molecular marker of prostate cancer since it is overexpressed in prostate biopsies from patients with this type of malignancy." (PMID 32471309, 2020). "More recent studies have shown that androgen receptors regulate prostate cancer cell migration via inhibition of TRPM8 and lowering of [Ca2+]i." (PMID 32825277, 2020). "Yang and colleagues observed that the overexpression of TRPM8 inhibits migration and proliferation of the androgen-independent prostate cancer cell line PC-3, also facilitating starvation-induced apoptosis." (PMID 33291725, 2020). "Over-expression of TRPM8 in PC-3 prostate cancer cells induced cell cycle arrest, facilitated starvation-induced apoptosis, and reduced migration, owing to the inactivation of focal adhesion kinase (FAK)." (PMID 32825277, 2020). "These pieces of evidence suggest that elevated TRPM8 promotes chemoresistance in prostate cancer and osteosarcoma cell lines." (PMID 32575381, 2020). "As a member of the TRP superfamily, TRPM8 channel, changes in its expression level is involved in the etiology of prostate cancers and it seems to be one of the most promising potential drug target channels in the treatment of prostate cancers." (PMID 30858386, 2019). "Our results demonstrate that encapsulating the TRPM8 agonist in LNC potentiated the inhibition of prostate cancer cell migration through the activation of the channel." (PMID 31138874, 2019). "Androgen-dependent expression of TRPM8 increases in both benign prostate hyperplasia and in prostate carcinoma cells." (PMID 30858386, 2019). "Such a radiotherapeutic approach of targeting prostate cancer cells expressing TRPM8 would be more accurate than surgery and decrease at the same time the associated side effects such including impotency and incontinence." (PMID 31138874, 2019). "The major findings of this study are that TRPM8 channel is separately activated in the prostate cancer cells by ADPR and oxidative stress and its sensitivity enhance to ROS." (PMID 30858386, 2019). "In prostate carcinogenesis, expression and/or activation of the Transient Receptor Potential Melastatin 8 channel (TRPM8) was shown to block in vitro Prostate Cancer (PCa) cell migration." (PMID 31138874, 2019). "The aim of this study was to use nanocarriers encapsulating a drug to efficiently activate TRPM8 channels to arrest prostate cancer cell migration." (PMID 31138874, 2019). "During the treatment of tumor cells including prostate cancer cells, increase of mitochondrial oxidative stress through activation of TRPM8 channels and mitochondrial dysfunction has been suggested to account in cancer cells the induction of apoptosis." (PMID 30858386, 2019). "As the expression and/or activation of TRPM8 suppresses prostate cancer cell migration, TRPM8 was pinpointed as potential molecular target antagonizing metastatic transition of prostate cancer." (PMID 31888223, 2019). "In turn, TRPM8 activation is increased by the increase of mitochondrial ROS production and then the prostate cancer cells are killed by the TRPM8 channel-induced overproduction of intracellular ROS, apoptosis and Ca2+ entry." (PMID 30858386, 2019).
prostate carcinoma (continued). "Overexpression and/or activity of TRPM8 channel was shown to suppress prostate cancer (PCa) cell migration." (PMID 31501416, 2019). "The TRPM8 channel is involved in prostate cancer progression, and has been proposed as a promising clinical target." (PMID 31888223, 2019). "The role of different TRPM members has been shown in various cancers such as prostate cancer for mostly TRPM8 and TRPM2, breast cancer for mostly TRPM2 and TRPM7, and pancreatic cancer for TRPM2/7/8 channels." (PMID 29875336, 2018). "In contrast, in PDAC cells and in prostate cancer cells TRPM8 function and expression reduces cell motility." (PMID 29772843, 2018). "For example, TRPM8 (initially named Trp-p8) was first been described in a screening experiment analyzing upregulated transcripts in prostate cancer tissue." (PMID 30248976, 2018). "The TRPM8 gene was described as a novel prostate-specific gene owing to the fact that its expression increased over the transformation of prostate cancer." (PMID 29875336, 2018). "In androgen-dependent prostate carcinoma, TRPM8 seems to act as an inhibitor of the migration of prostate cancer cells by inactivating focal adhesion kinase in conjunction with partner proteins." (PMID 29875336, 2018). "In prostate cancer LNCaP cells, TRPM8 acts as a Ca2+-permeable channel and is expressed in the endoplasmic reticulum and plasma membrane." (PMID 28645930, 2017). "The evaluation of the TRPM8 expression pattern in prostate cancer patients further confirmed the incidence of TRPM8 removal from the plasma membrane and its internalization pattern coincided with the severity of the tumor." (PMID 28039451, 2017). "Screening all the immunoprecipitated proteins using mass spectrometry enabled a tool to construct a comprehensive global view on TRPM8 turnover in the prostate cancer cells." (PMID 28039451, 2017). "This scheme indicates that TRPM8 hydrolysis in the prostate cancer cells is maintained via both proteolytic mechanisms." (PMID 28039451, 2017). "The presence of TRPM8 mRNA in prostate cancer at high expression levels attracted attention towards this channel as an opportunistic prognostic marker." (PMID 28039451, 2017). "High-throughput proteome analysis revealed that TRPM8 degradation is enhanced in human prostate cancer cells." (PMID 28039451, 2017). "TRPM8 plays an important role in the pathophysiology of prostate cancer and is considered an ionotropic testosterone receptor." (PMID 28645930, 2017). "In prostate cancer, TRPM8 mRNA abundance and TRPM8 channel surface expression are upregulated by androgens, in breast cancer by estrogens." (PMID 29221175, 2017). "A high-throughput proteome analysis in the present study uncovered the molecular mechanism of TRPM8 biogenesis in the prostate cancer cells." (PMID 28039451, 2017). "In the present work, we documented that the TRPM8 expression profile indeed undergoes substantial rearrangements during prostate cancer progression, and the protein localization is significantly altered." (PMID 28039451, 2017). "Previous studies also demonstrated TRPM8 localization in the ER membrane of a prostate cancer-derived epithelial cell line (LNCaP)." (PMID 28861042, 2017). "While visualizing TRPM8 expression patterns in the prostate tissue array, we found that the degree of TRPM8 internalization increased gradually along with the severity of the prostate cancer, which was assessed by the Gleason score value." (PMID 28039451, 2017). "Here we have studied the role of these regulatory sM8s subunits of TRPM8 in prostate cancer survival." (PMID 27074561, 2016). "Several studies have demonstrated both plasma membrane and endoplasmic reticulum (ER) membrane TRPM8 expression, in prostate cancer cell lines that are androgen-sensitive, such as LNCaP cells (Lymph Node Carcinoma of the Prostate)." (PMID 27409624, 2016). "For instance, TRPV2, TRPV6, and TRPM8 were differentially expressed between normal prostate and prostate carcinomas." (PMID 27023518, 2016).
prostate carcinoma (continued). "Since its cloning a decade ago, TRPM8 channel has emerged as a promising prognostic marker and a putative therapeutic target in prostate cancer (PCa)." (PMID 27074561, 2016). "Its androgen-dependent expression increases in both benign prostate hyperplasia and in prostate carcinoma cells, which both presented high androgen levels, while anti-androgen therapy greatly reduces the expression of TRPM8." (PMID 27409624, 2016). "Nevertheless, it has to be noted that contrasting results concerning the role of TRPM8 in cell migration have been shown using pharmacological agents inhibiting TRPM8, which have led to a reduction in the speed of prostate cancer cells." (PMID 27409624, 2016). "Recently, we cloned and characterized this truncated TRPM8 channel isoform in membranes of the endoplasmic reticulum (ER) from human prostate cancer cells and keratinocytes." (PMID 27074561, 2016). "Several lines of evidence have been discovered over recent decades showing the importance of TRPM8 in prostate cancer." (PMID 27409624, 2016). "The proliferative role of TRPM8 in cancer cells is also demonstrated in AR+ prostatic carcinoma (LNCaP), osteosarcoma (MG-63 and U2OS), and colon cancer (Caco-2) cell lines." (PMID 26512697, 2015). "In agreement with this, TCAF1 that facilitates opening of the TRPM8 channel has been demonstrated to impede prostate cancer cells migration." (PMID 26512697, 2015). "The proliferative role of TRPM8 in prostate cancer is further supported by TRPM8-mediated promotion of tumor growth under hypoxic condition in vitro." (PMID 26512697, 2015). "On the contrary, ectopic expression of TRPM8 in AR− prostate cancer cells impaired cell migration through inactivation of focal adhesion kinase." (PMID 26512697, 2015). "In the cell lines derived from pancreatic adenocarcinoma, AR+ prostatic carcinoma, osteosarcoma, and colon cancer, TRPM8 is required for sustaining cellular proliferation." (PMID 26512697, 2015). "Both the pharmacological blockade and the siRNA-mediated silencing of TRPM8 channels have been shown to induce the apoptotic death of prostate cancer cells, indicating a critical role for these channels in Ca2+ homeostasis maintenance." (PMID 25710007, 2015). "In a recent report, TRPM8-promoted hypoxic tumor growth in AR+ prostate carcinoma cells involves RACK1 binding to HIF-1α and RACK1-mediated ubiquitination of HIF-1α." (PMID 26512697, 2015). "In the AR+ prostate cancer cell line LNCaP, siRNA-mediated knockdown of TRPM8 or using a chemical blocker of TRPM8 (capsazepine) reduced cell viability (by MTT assay) and induced apoptotic nuclei." (PMID 26512697, 2015). "In the AR+ prostatic carcinoma and osteosarcoma cell lines, anti-TRPM8 siRNA reduced cellular proliferation and impaired cell cycle progression with arrest in the G0/G1 phases." (PMID 26512697, 2015). "This notion is further demonstrated by the in vivo studies showing that over-expression of TRPM8 in the AR+ and TRPM8-expressing LNPaC cells promoted tumorigenicity of xenograft prostate cancer." (PMID 26512697, 2015). "LNCaP prostate cancer cell line was used as TRPM8-positive control to assess the exact band size, and β-actin was used as loading control." (PMID 24593692, 2014). "Zhang and colleagues showed that disruption of calcium homeostasis through inhibition of the permeable ion channel TRPM8 reduced viability of LNCaP prostate cancer." (PMID 25344862, 2014). "In particular overexpression of TRPM8 in prostate cancer cells reduces the cell motility through the inactivation of FAK." (PMID 24204345, 2013). "Mice transplanted with prostate cancer cells over-expressing TRPM8 develop tumours that are less vascularized than control." (PMID 24204345, 2013). "Despite the growing literature regarding the physiological role of TRPM8, its role in the oncogenesis of prostate cancer remains poorly understood." (PMID 23251635, 2012).
prostate carcinoma (continued). "Mislocalization of TRP channels is also seen in cancer cells, with the expression of functional TRPM8 channels on the ER of prostate cancer cells." (PMID 22666335, 2012). "Human TRPM8 was initially identified during a screen for up-regulated genes in prostate cancer (and therefore termed trp-p8 but later detected in other tumor types." (PMID 23251635, 2012). "Recent studies have also shown that TRPM8 is markedly expressed in visceral organs, predominantly in prostate and liver and, more importantly, it is highly upregulated in prostate cancer cells." (PMID 23203269, 2012). "Recent evidence indicates that TRPM8 activity is a relevant factor controlling migration of prostate cancer cells." (PMID 23251635, 2012). "TRPM8 mRNA has been detected in malignant cells, and this has been extensively studied in prostate cancer." (PMID 23251635, 2012). "Collectively, the results obtained with the different blockers are consistent with the view that inhibition of TRPM8 results in a reduced proliferation in prostatic cancer cells." (PMID 23251635, 2012). "We observed no consistent acceleration of growth after stimulation of the channel with menthol or icilin, indicating that basal TRPM8 expression is enough to sustain growth of prostate cancer cells." (PMID 23251635, 2012). "A growing body of evidence supports the idea that the expression of TRPM8 in prostate cancer can be used as a prognostic marker and a tool for the design of novel cancer therapies." (PMID 23251635, 2012). "This limits the use of such blockers in the study of the role of TRPM8 in prostate cancer because the cells express also TRPV1." (PMID 23251635, 2012). "Previous studies described the overexpression of TRPM8 in prostate tumors and cell lines derived from prostate cancer, specifically LNCaP." (PMID 23251635, 2012). "Our data are consistent with the notion that TRPM8 plays a relevant role in prostate cancer progression." (PMID 23251635, 2012). "Our results confirm the notion that TRPM8 inhibition reduces cell proliferation of prostate cancer cells." (PMID 23251635, 2012). "Several studies have provided evidence of a pronounced TRPM8 expression in human tumours including prostate cancer, melanoma, lung cancer, colorectal adenocarcinoma and breast cancer." (PMID 20482834, 2010). "TRPM8 was initially identified in prostate and found to be up-regulated in prostate cancer; it was thought to be a prostate specific gene." (PMID 19582168, 2009). "Moreover, a recent study showed that prostate cancer cells secrete the Transient Receptor Potential Cation Channel Subfamily M Member 8 (TRPM8) into extracellular vesicles, which then function as a TLR3 agonist." (PMID 41601666, 2026). "Oxidative stress could activate the TRPM8 channel to induce Ca2+ and pro-apoptotic signals in prostate cancer." (PMID 40823088, 2025). "The TRPM8 partially inhibits prostate cancer cell migration." (PMID 40922741, 2025). "Furthermore, prostate cancer xenografts expressing a translation-defective form of TRPM8 RNA contain less collagen type I in the extracellular matrix, significantly more infiltrating NK cells, and larger necrotic areas as compared to control xenografts." (PMID 38316991, 2024). "TRPM8 was initially identified in prostate tissue and reported as upregulated in prostate cancer." (PMID 39108834, 2024). "In vivo, when transplanted in BALB/c nude mice, LNCaP prostate cancer cells experiencing TRPM8 RNA-induced sterile inflammation form tumors characterized by low collagen I deposition, high numbers of infiltrating Natural Killer (NK) cells, and widespread necrosis." (PMID 38316991, 2024). "It is suggested that channel activation with TRPM8 agonist in nanocarriers could be used in the early stages of prostate cancer to decrease tumor cell dissemination." (PMID 37033630, 2023).
prostate carcinoma (continued). "In addition, menthol has exerted the anti-tumor activity in prostate cancer DU145 cells via upregulating the TRPM8 expression by menthol, which leads to anti-proliferation and inhibition of motility." (PMID 36923503, 2023). "In addition to the protective effect of TRPM8 in prostate cancer, it was demonstrated the advantage of using nanocarriers on the improved activity of the channel agonist, as encapsulation decreased the concentration required to activate the channel." (PMID 37033630, 2023). "Beside this well know role in thermal transduction, the human TRPM8 gene was first identified and cloned from prostate tissues and described as a new prostate-specific gene due to the peculiar expression pattern shown during prostate cancer (PCa) progression." (PMID 37576340, 2023). "Furthermore, by using the agonist WS12 inside lipid nanocapsules, the authors demonstrate that TRPM8 activation decreases cell migration, and metastasis, suggesting a protective role of the channel on prostate cancer progression." (PMID 37033630, 2023). "TRPM8 is a promising therapeutic target in advanced prostate cancer." (PMID 37240443, 2023). "In bone, bladder, prostate cancer, and glioblastoma, TRPM8 regulates the expression of ERK1/2." (PMID 37033630, 2023). "Additionally, TRPM8 Ca2+ signaling appears to be essential for the physiopathology of prostate cancer." (PMID 35976012, 2022). "Furthermore, androgens were known to regulate transient receptor potential melastatin 8 (TRPM8) protein expression through AR activation in prostate cancer development, and TRPM8 activity was reported to suppress prostate cancer cell migration." (PMID 37435453, 2022). "Overall, this study reinforces the hypothesis that activating TRPM8 could play a protective role in prostate cancer progression, thus supporting its potential application as a powerful therapeutic target antagonizing the metastatic transition of PCa." (PMID 35743115, 2022). "A final set of experiments was performed to evaluate whether the mechanistic model illustrated here on the TRPM8-Rap1 interaction could potentially be generalized beyond prostate cancer." (PMID 35565390, 2022). "Because patients with chronic prostatic hyperplasia often develop prostate cancer, they may benefit from TRPM8 activator therapy." (PMID 35919815, 2022). "Based on these results, a TRPM8 splice variant, found in prostate cancer cells and lacking the first 65 residues, was also studied." (PMID 35976012, 2022). "Moreover since some studies suggest a correlation between TRPM8′s role in prostate cancer progression and the androgen–dependent state of PCa cells, the efficacy of LNC–WS12s needs to be tested on androgen–dependent PCa cells." (PMID 35743115, 2022). "In the fight against prostate cancer (PCa), TRPM8 is one of the most promising clinical targets." (PMID 35743115, 2022). "Moreover, we found group-enriched (liver and prostate) TRP gene TRPM8 also exhibited higher expression in liver and prostate cancer." (PMID 35614079, 2022). "Since its first identification in prostate cancers and prostate tissues, transient receptor potential melastatin-subfamily member 8 (TRPM8) is subsequently found to be overexpressed in a wide range of cancers and is shown to be implicated in tumorigenesis and tumor progression." (PMID 35361751, 2022). "Since the individuation of this channel in prostate cancer cells, numerous studies have confirmed the dysregulation of TRPM8 in the plasma of cancer cells in breast, bladder, esophageal, lung, human osteosarcoma, skin, pancreas, colon, and other gastric cancers." (PMID 34445208, 2021). "Transient receptor potential melastatin-8 (TRPM8) represents an emerging target in prostate cancer, although its mechanism of action remains unclear." (PMID 34853378, 2021). "Moreover, TRPM8 inhibition and silencing reduce proliferative capacity in pancreatic adenocarcinoma and prostate cancer cells." (PMID 33614639, 2021).